IL1B (interleukin 1 beta)
Diseases named in the same sentence as IL1B in open-access papers (continued):
Sharing a sentence is not in itself a finding about the gene and the disease.
Cognitive impairment (continued). "The mediation analysis showed that IL-1β and IL-18 could explain 25.4 and 17.5% of effect of the risk of cognitive impairment related to 25(OH)D3 deficiency." (PMID 35370605, 2022). "Ultimately, mediation analysis suggested that IL-1β and IL-18 could explain 25.4 and 17.5% of effect of the risk of cognitive impairment related to 25(OH)D3 deficiency." (PMID 35370605, 2022). "A suggestion that could be driven from this study is that NLRP3/IL-1β signaling could underlie correlations between visceral adiposity and cognitive impairment not only in mice but also in humans." (PMID 34070553, 2021). "NLRP3/IL-1β signaling could underlie the association between adiposity and cognitive impairment in humans." (PMID 34070553, 2021). "Thus, hippocampal IL-33 induced an inflammatory state, including IL-1β overexpression by microglia cells, being causative of the cognitive impairment." (PMID 32917228, 2020). "In addition, Brain derived neurotrophic factors (BDNF) and pro-inflammatory cytokines (e.g., Interleukin-1 beta) are implicated in cognitive impairment and dementia." (PMID 32047732, 2019). "Thus, small litter size induced cognitive impairment in NMRI mice is associated with higher levels of IL-1β and lower levels of BDNF in the hippocampus." (PMID 30050150, 2018). "Some proinflammatory cytokines, such as IL-1β and IL-6, have been associated with reduced amyloidosis and amelioration of cognitive deficits in APP mouse models, and may contribute to the beneficial effects of FUS in AD." (PMID 30232364, 2018). "Moreover, a large number of cognitive disorders in humans and animal models are associated with elevated levels of proinflammatory molecules, such as IL-1β and TNF-α." (PMID 24205200, 2013). "Moreover, elevated IL-1β production is associated with AD pathology, and its reduction may alter brain inflammatory responses and alleviate cognitive deficits." (PMID 40563933, 2025). "In addition to serving as pivotal pro-inflammatory cytokine in the innate immune response, IL-1β also plays a critical role in the pathogenesis of a variety of CNS diseases associated with cognitive impairment, such as epilepsy, stroke, schizophrenia, and autism." (PMID 38665289, 2024). "However, excessive IL-1β is associated with cognitive deficits." (PMID 37834141, 2023). "Pro-inflammatory cytokines, such as Il-1β, play an important role in neurogenesis, synaptic plasticity, and memory formation and consolidation at basal levels; however, elevated levels of these cytokines in the CNS are linked with behavioral and cognitive impairments, including depression." (PMID 36042284, 2022). "Additionally, we found that mdivi-1, an inhibitor of mitochondrial fission that further affects cellular physiology in ways that are independent of mitochondrial fusion, prevented the increases in expression of Drp1 and IL-1β and attenuated cognitive deficits caused by AβOs in mice." (PMID 33612100, 2021). "Therefore, we hypothesize that canonical NLRP3 inflammasome/IL-1β axis is likely is implicated in postoperative inflammatory mediators-induced cognitive impairment." (PMID 30873011, 2019). "Specifically, cytokines like IL-1β and associated angiogenic modulators are reported to be a crucial component of brain and systemic degeneration processes in aging and in degenerative diseases, such as conversion from Mild Cognitive Impairment into Alzheimer's disease." (PMID 26286955, 2015). "In this regard, a relevant observation is the consistency of the elevation of inflammatory cytokines IL-6, IL-13, IL-8, IL-1β, and TNFα at the longest phase of follow-up related to cognitive deficits and/or post-acute sequelae." (PMID 41516418, 2026). "IL-6, TNF-α, and IL-1β levels during chronic neuroinflammation or cognitive impairment represent chronic neuroinflammation or cognitive impairment." (PMID 41516374, 2026).
Cognitive impairment (continued). "Upon administration, LPS activates microglia and astrocytes, which trigger pro-inflammatory modulators (IL-1β, IL-6, and TNF-α), causing the progression of neurological complications such as cognitive impairment." (PMID 41557677, 2026). "Bacillus subtilis administration prevented cognitive deficits, maintained Tnfa at control levels, and significantly reduced Il1b and Il6 expression compared to the LPS + ZDV group." (PMID 41892682, 2026). "Studies of SARS-CoV-2 infection in animals and humans have shown an infiltration of activated monocytes into the brain with microglial activation and an increase in brain IL-1β that decreased neurogenesis and promoted cognitive impairment." (PMID 41369364, 2025). "The critical role of interleukin-1 beta (IL-1β) is demonstrated by studies where intracerebroventricular administration of an IL-1β receptor antagonist mitigates sevoflurane-induced cognitive deficits in rodents." (PMID 41561335, 2025). "Anakinra serves as an IL-1β receptor antagonist that decreases neuroinflammation, cognitive impairment, and tau phosphorylation, while canakinumab neutralizes IL-1β and prevents its proinflammatory effects." (PMID 39891777, 2025). "Behavioral analyses of IL-1β-exposed animals reveal various cognitive deficits, including memory impairment, anxiety-like behaviors, and social interaction deficits, but without motor disabilities." (PMID 40909354, 2025). "A recurring finding was the elevation of pro-inflammatory cytokines (i.e., IL-1β, IL-6, TNF-α) together with reduced BDNF levels, frequently associated with cognitive deficits in both healthy and tumor-bearing models." (PMID 41155372, 2025). "A recent study found that the probiotic Lactobacillus gasseri mediates gut-brain signaling through the VN, alleviating cognitive impairment and depression in mice while improving Escherichia coli (E. coli)-induced gut dysbiosis and inhibiting IL-1β expression." (PMID 40657642, 2025). "TNF-α and IL-1β appear to play a significant role in cognitive decline in patients with Alzheimer’s disease and mild cognitive impairment, showing potential to distinguish between different stages of Alzheimer’s." (PMID 40711681, 2025). "Significantly higher levels of IL-1β were detected in adults with Alzheimer’s disease compared to individuals with Mild Cognitive Impairment and controls with normal cognition." (PMID 40711681, 2025). "Peripheral inflammation elevates brain pro-inflammatory cytokines (e.g., IL-1β, TNF-α), exacerbating neuroinflammation-associated cognitive deficits in encephalopathy patients." (PMID 41291751, 2025). "Multiple studies have reported elevated TNF⍺, IL6, IL1β, and hyperactive microglia in AD patients with early mild cognitive impairment (MCI), contributing to LTP impairment via Aβ-induced proinflammatory cytokines." (PMID 40498003, 2025). "When comparing studies using chemotherapy in healthy versus tumor-bearing animal models, both groups exhibited a consistent pattern of cognitive impairment accompanied by increased levels of pro-inflammatory cytokines, particularly IL-1β, IL-6, and TNF-α." (PMID 41155372, 2025). "Blocking IL-1β was able to prevent cognitive impairment and reduce tau pathology and Aβ synthesis in a mouse model of AD." (PMID 39891777, 2025). "Hydrophilic ursodeoxycholic acid (UDCA, as a therapeutic bile acid) exerts dual neuroprotection by activating TGR5 and inhibiting NOD-like receptor family pyrin domain containing 3 (NLRP3)/IL-1β, reducing infarct size and cognitive deficits." (PMID 40895486, 2025). "In a mild TBI model, it was found that MW151 administration can inhibit acute cytokine upregulation (such as IL‐1β), protect glial cell responses (microglia and astrocytes), and alleviate downstream cognitive impairment." (PMID 40824273, 2025).
Cognitive impairment (continued). "The inflammatory response facilitates cell-to-cell transmission of the αSyn protein via IL-1β/IL-1 receptor 1-dependent signaling, resulting in cognitive impairments and motor dysfunction." (PMID 39860410, 2025). "Specifically, cognitive impairment induced by IL-1β in AD mouse models can be reversed by the IL-1 receptor antagonist anakinra." (PMID 40153574, 2025). "Ursolic acid can also inhibit the activation of microglia and astrocytes and reduce the levels of TNF–α, IL–1β, and IL–6 in the brain inflammation of mice with lipopolysaccharide–induced cognitive deficits." (PMID 40005889, 2025). "Increased levels of serum TNF-α and IL-1β correlate with an accelerated rate of cognitive impairment in AD patients." (PMID 40847374, 2025). "Neuroinflammation featured by the overactivation of glial cells, robustly produced a body of neuroinflammatory factors, including TNF‐α, IL‐6, IL‐1β and NO, etc., and subsequently led to neuronal damage and cognitive impairment." (PMID 37697966, 2024). "The severity of cognitive impairment correlated with plasma IL-1β and TNFα levels and serum IL-6 levels." (PMID 39769285, 2024). "Our past work also suggests a role for interleukin-1 beta (IL-1β) in cognitive deficits after closed head injury (CHI) in mice." (PMID 38435077, 2024). "Specific knockdowns of IL-1β or KCC2 expression can reverse this severe inflammation-induced cognitive impairment." (PMID 38665289, 2024). "Consistent with our results, sitagliptin (600 mg/kg/day, 90 days, PO) reduced cognitive impairment and brain damage in rats suffering from chronic cerebral hypo-perfusion by decreasing inflammation via attenuating IL-1β, TNF-α, and other inflammatory factors." (PMID 38333747, 2024). "The activation of astrocytes and microglia has been widely acknowledged to contribute to cognitive impairment through the release of proinflammatory mediators, including IL-1β and TNF-α." (PMID 38991663, 2024). "We found that IL1β, P-tau, and T-tau levels increased with age and were strongly correlated with the severity of cognitive deficits." (PMID 39109268, 2024). "Preclinical and clinical studies have both shown that cognitive impairment induced by AD is accompanied by elevated levels of pro-inflammatory cytokines including interleukin-1 beta (IL-1β), IL-6, and tumor necrosis factor-alpha (TNF-α)." (PMID 38231482, 2024). "The mice exhibited cognitive impairment accompanied by increased expression of proinflammatory factors (IL-1β, TNF-α), proapoptotic molecules (caspase-3, bax) and microglial activation in the hippocampus 1, 3 and 7 days after surgery." (PMID 37973625, 2024). "For example, CX3CR1 knock-out mice showed increased levels of IL-1β, cognitive impairment, and reduced LTP." (PMID 37548934, 2024). "Activating microglia, enhancing the expression of TNF-α and IL-1β in vitro, and resulted in cognitive impairment, Aβ deposition and Tau hyperphosphorylation in the mouse cerebrum." (PMID 38362505, 2024). "QCLG improved weight loss, cognitive impairment, neurological function scores, blood ammonia, and brain gene expression of interleukin-6 (TNF-α), Interleukin-1β (IL-1β), and interleukin-6 (IL-6) induced by HE." (PMID 39220284, 2024). "Cognitive impairment, represented by reduced place recognition memory that is accompanied by hippocampal upregulation of mRNA levels of IL-1β, IL-6, and TNF-α, has also been recently observed in HFD and fiber-deficient diet mice." (PMID 37432552, 2023). "The production of proinflammatory cytokines, such as TNF‐α, IL‐6, and IL‐1β, further aggravates the neuroinflammatory response and leads to cognitive disorder." (PMID 37550899, 2023). "In summary, the results show that the activation of the NLRP3/Caspase-1/IL-1β signaling pathway negatively regulates the hippocampal neuroinflammation and cognitive impairment induced by LPS." (PMID 36934348, 2023).
Cognitive impairment (continued). "Collectively, our findings provide novel mechanistic evidence on the role played by HSV-1-activated IL-1β signaling pathways in synaptic deficits leading to cognitive impairment." (PMID 37261502, 2023). "Psychological distress was involved in chemotherapy‐related cognitive impairment (CRCI) by increasing IL‐1β, TNF‐α, and IL‐4 levels." (PMID 36965094, 2023). "Our study identifies IL-1β as one potential mechanism driving SARS-CoV-2-induced cognitive impairment in a new murine model that is prevented by vaccination." (PMID 37790551, 2023). "Among the key targets, increased levels of the inflammatory cytokines interleukin-6 (IL6), tumor necrosis factor (TNF), and interleukin-1β (IL1B) all independently contribute to cognitive impairment." (PMID 37233418, 2023). "Few clinical studies also shown that chemotherapy-induced IL-17, IL-1β, and GM-CSF expression in cancer patients are more prominent who faced cognitive impairment." (PMID 37631080, 2023). "Two studies showed that caspase-1-mediated overproduction of IL-1β occurred in brain samples from mild cognitive impairment (MCI) and fully symptomatic AD patients." (PMID 37189617, 2023). "In this study, we explored the potential role of the Hsp22/NLRP3/Caspase-1/IL-1β axis in LPS-induced hippocampal neuroinflammation and cognitive impairment in mice." (PMID 36934348, 2023). "Increased presence of IL-1B is also seen in Alzheimer’s disease as well as in mild cognitive impairment." (PMID 37965360, 2023). "The increment of major pro-inflammatory cytokines, including IL-1β and TNFα, plays a crucial role in neuroinflammation and cognitive impairment in AD." (PMID 35439990, 2022). "This study showed that CHRE improved cognitive impairments in Aβ1–42-induced rats through decreased Aβ1–42 protein levels and neuroinflammation, particularly the expressions of CD11b-positive microglia, IL-1β, and TNFα in the cerebral cortex and hippocampus." (PMID 35439990, 2022). "Simultaneously, other research does not find a strict positive correlation between the severity of positive symptoms, cognitive deficits and enhanced levels of proinflammatory cytokines, such as IL-6, IL-1β and TNF-α." (PMID 36139363, 2022). "In AD, the activation of microglia caused by Aβ accumulation is followed by the synthesis and release of pro-inflammatory cytokines, including interleukin-1β (IL-1β) and tumor necrosis factor-α (TNFα), and ultimately leads to cognitive impairments." (PMID 35439990, 2022). "IL-1β neutralizing antibodies or knockout of the IL-1 receptor can improve postoperative cognitive impairment in aged mice, suggesting the necessity and importance of producing PNDs." (PMID 35721159, 2022). "We found that SCH58261 inhibited microglial activation and decreased the levels of TNF-α, IL-1β and IL-6, ultimately alleviating cognitive impairment in CP mice." (PMID 36234803, 2022). "Accordingly, specific knockdown of IL-1β or KCC2 expression improved the cognitive impairment induced by neonatal severe inflammation." (PMID 35883093, 2022). "Injection of recombinant IL-37 into WT mice showed restoration of cognitive deficits and reduced release of pro-inflammatory cytokines after IL-1β-mediated immunostimulation." (PMID 36040311, 2022). "Conversely, bilateral intrahippocampal injection of IL-33 (400 ng) induced IL-1β overexpression by microglia cells and cognitive impairment in mice." (PMID 36138980, 2022). "Studies showed NLRP1 expression was up-regulated in the brain tissue of APP/PS1 mice, however, using NLRP1 inhibitor decreased caspase-1 and IL-1β expression, reduced neuron pyroptosis, and finally improved cognitive impairment." (PMID 35782390, 2022). "In line with upregulated IL‐1β in CMECs, microglial cells were activated through IL‐1R1/pNF‐κB pathway and resulted in neuroinflammatory response and cognitive impairment." (PMID 34837343, 2022).
Cognitive impairment (continued). "Their neurotoxic effects in ischemic stroke have been reported, and blocking IL-1β has been shown to reduce ischemic brain damage and cognitive impairment." (PMID 36004858, 2022). "More importantly, hyperforin treatment significantly reduced Aβ deposition, GFAP expression, levels of IFN-γ, IL-1β, IL-6, and TNFα, and improved performance in behavioral tests, suggesting reversal of cognitive deficits." (PMID 35077394, 2022). "The ATOR treatment can also potentiate the neuroinflammatory process via the activation of NLRP3 and its subsequent mediator IL1B-inducing cognitive impairment." (PMID 35335908, 2022). "To further elucidate the effect of BTL-I on AlCl3-induced cognitive impairment in zebrafish, we assessed changes in the levels of several biochemical indicators (including IL-1β, TNF-α, GSH, AChE)." (PMID 35130930, 2022). "Th overexposure to IL-1β, another major pro-inflammatory cytokine, can lead to substantial neuronal damage and worsen cognitive impairment by synaptic damaging." (PMID 35563317, 2022). "This study also revealed that MCC950 treatment decreased the level of IL-1β and ameliorated cognitive impairment in the surgery model." (PMID 35955939, 2022). "A previous study suggested that the levels of CRP, TNF-α, IL-1β, IL-6, and IL-8 in the peripheral blood of patients with mild cognitive impairment (MCI) were higher than those in the normal population." (PMID 36590060, 2022). "For MWM test, treatment with IL-1β-siRNA significantly improved neonatal inflammation-induced cognitive impairment (n= 15–24, *P = 0.012, ** P < 0.01, *** P < 0.001)." (PMID 35883093, 2022). "After EE, HDAC and DNMT enzyme activity decreased, cognitive impairment was reversed, IL1-β levels decreased and there was an increase in PSD-95 levels in the hippocampus." (PMID 35798809, 2022). "Scopolamine-treated mice have already been shown to have elevated levels of inflammatory cytokines (e.g., TNF-α, IL-1β, and IL-18) and cognitive impairment." (PMID 36294963, 2022). "Hyperactivated NLRP3 inflammasome and IL-1β-mediated inflammatory responses in microglia are involved in hypoxemia and isoflurane-induced cognitive impairment in adult rats." (PMID 36456961, 2022). "BDNF-pathway has been indicated as a mediator between neuroinflammation and cognitive impairment, and also IL-1β played a crucial role in regulation of BDNF levels." (PMID 35370607, 2022). "IL-1β has similar functions as TNF-α, which is associated with mTBI-related cognitive impairment in acute working memory." (PMID 35153973, 2021). "The role of inflammatory cytokines, especially TNF-α, IL-1β, IL-6, and IL-8, is well-established in neurodegeneration and cognitive deficits." (PMID 34103066, 2021). "TNF-α and IL-1β in the ischemic brain can reportedly induce the production of IL-6, and increased IL-6 levels in the serum and cerebrospinal fluid are related to cognitive impairment." (PMID 34457113, 2021). "Increase IL-1β secretion in the hippocampus lead to the impairment of synaptic plasticity, cognitive deficits, and mood disorders, which has been seen in Cx3cr1 deficient adult mice." (PMID 34720877, 2021). "In turn, cognitive impairment seems to correlate with peripheral levels of IL-1β, IL-4, IL-6 and IL-12, and considering only the AChR population, also with peripheral levels of TNF-α." (PMID 34501305, 2021). "IEC-derived exosomes induce M1 polarization that subsequently mediated the secretion of IL-1β in MLNs and in the peripheral circulation, resulting in cognitive impairment, inflammation, and hippocampal damage in SAE rats." (PMID 35111693, 2021). "TNF-α and IL-1β expression were positively correlated with cognitive impairment-like behaviors and Prevotellaceae and Bacteroidales populations in the gut microbiota." (PMID 34579150, 2021). "The up-regulation of IL-1β level in thehippocampus region showed the interfering of long-term potentiating that induce cognitive impairment." (PMID 34308580, 2021).